CASR (calcium sensing receptor)
Diseases named in the same sentence as CASR in open-access papers (continued):
Sharing a sentence is not in itself a finding about the gene and the disease.
pulmonary hypertension (14 papers, 2011 to 2025). Increased pressure within the pulmonary circulation due to lung or heart disorder. "TRPC6 channels have been previously linked to CaSR-induced contraction, proliferation and migration of VSMCs in pulmonary arterial hypertension, and to CaSR-mediated rises in [Ca2 +]i in human aortic VSMCs." (PMID 28867591, 2017). "Previously, CaSR signaling has been implicated in the proliferative and remodeling processes of diseases, such as asthma, cardiac fibrosis, pulmonary arterial hypertension (PAH), and chronic obstructive pulmonary disease (COPD), some of which are common IPF comorbidities." (PMID 40305220, 2025). "We also found that U50,488H interacted with the calcium-sensing receptor (CaSR) in the pulmonary artery and inhibited pulmonary hypertension and vascular remodeling through the CaSR/MAPK signaling pathway." (PMID 34016793, 2021). "Pharmacologically blockade of CaSR significantly attenuate the development and progression of experimental pulmonary hypertension in animals." (PMID 27867361, 2016). "Pharmacological blockade and targeted deletion of CaSR has been shown to inhibit the CaSR-mediated increase in [Ca2+]cyt and attenuates the development of experimental-induced pulmonary hypertension in animal models of the disease." (PMID 27867361, 2016). "In asthma and pulmonary hypertension, direct activation of CaSR with the polyamines and/or polycationic proteins increases cytosolic calcium signaling, smooth muscle cell proliferation, and hyperresponsiveness, all of which are abolished by genetic or pharmacological inhibition of CaSR." (PMID 40305220, 2025). "Polyamines are agonists of the calcium/cation-sensing receptor (CaSR), activation of which is detrimental for asthma and pulmonary hypertension, but its role in IPF is unknown." (PMID 40305220, 2025). "A proposed mediator for some forms of pulmonary hypertension is CaSR in pulmonary vasculature." (PMID 35054903, 2022). "However, under some pathological conditions, such as pulmonary hypertension, myocardial ischemia, and cardiac hypertrophy, CaSR expression is upregulated, leading to [Ca2+]i enhancement and thus aggravating the progression of these diseases." (PMID 30364197, 2018). "Moreover, the CaSR in the cardiovascular system plays an important role in pulmonary hypertension, atherosclerosis, and ischemia/reperfusion injury." (PMID 30364197, 2018). "Thus, the present study investigated the expression of CaSR in PAMSCs as well as the effect of CaSR activation on pulmonary artery tension in order to provide an experimental basis for the mechanism of pulmonary hypertension involved by CaSR." (PMID 21314926, 2011). "Pulmonary artery constriction contributes to pulmonary hypertension, so it is expected that CaSR activation could be involved in the development of pulmonary hypertension.." (PMID 21314926, 2011). "Furthermore, binding of HIMF with calcium-sensing receptor stimulates pulmonary hypertension." (PMID 33800244, 2021). "Other signaling mechanisms such as extracellular calcium sensing receptor (CaSR) and peroxisome-proliferator activated receptor-γ (PPAR-γ) are also involved in the pathogenesis of pulmonary hypertension and remodeling through SOCE." (PMID 29867539, 2018). "Our group has previously shown that expression of CaSR, a member of the GPCR family, is upregulated in PASMC isolated from IPAH patients and in animal models of pulmonary hypertension." (PMID 27867361, 2016). "However, CaSR can also bind to a hypoxia-induced mitogenic factor (HIMF), resulting in pulmonary vascular remodeling and pulmonary hypertension." (PMID 36077479, 2022). "CaSR are overexpressed in proliferating PASMC from hypoxic rodents or from patients with idiopathic pulmonary hypertension (IPAH), while their pharmacological or genetic suppression reduce proliferation and pulmonary hypertension." (PMID 29867539, 2018).
pulmonary hypertension (continued). "While it has been demonstrated that both CaSR and TRPC6 are upregulated in PASMC from IPAH patients and animals with experimental pulmonary hypertension and play a critical role in the pathogenesis of PAH, it remains unknown how this is achieved." (PMID 27867361, 2016).
vitamin D deficiency (14 papers, 2011 to 2026). A nutritional condition produced by a deficiency of VITAMIN D in the diet, insufficient production of vitamin D in the skin, inadequate absorption of vitamin D from the diet, or abnormal conversion of vitamin D to its bioactive metabolites. "In low-bone-turnover disease, vitamin D deficiency directly reduces CaSR expression by downregulating these receptors." (PMID 36015101, 2022). "Disturbances of Ca2+ homeostasis can be caused by various mechanisms, such as excessive calcium intake in the diet, vitamin D deficiency, structural and functional changes in vitamin D receptor, changes in Ca2+ channels and Calcium-Sensing Receptor (CaSR)." (PMID 32252342, 2020). "This cross-sectional study was conducted in subjects with vitamin D deficiency (VDD) to observe associations between CaSR polymorphisms, plasma iPTH, and serum calcium levels." (PMID 25695075, 2015). "Possible causes of the more severe phenotype seen in these cases include the specific type of CaSR gene mutation, paternal versus maternal inheritance, prematurity and maternal vitamin D deficiency." (PMID 22620673, 2012). "We proposed the possibility that a patient with CaSR mutation may tend to present with skeletal phenotype of rickets under conditions of vitamin D deficiency." (PMID 28690912, 2017). "Our study revealed that rickets-like features have a tendency to present atypically in FHH patients who have a mild vitamin D deficiency, and that CaSR mutations may have a partial role in the pathogenesis of skeletal deformities." (PMID 28690912, 2017). "We postulated that CaSR expression in circulating monocytes could be particularly useful to follow the impact of vitamin D deficiency and/or pro-inflammatory cytokines." (PMID 24098349, 2013). "Decreases in CaSR expression within the parathyroid glands and vasculature potentiate the hazards of SHPT because of the corresponding vitamin D deficiency and dysregulation of the proteins for cell cycling." (PMID 36015101, 2022). "Vitamin D deficiency and progressive reductions in serum calcitriol in the course of CKD also impair the response of the parathyroid gland to calcium due to reductions in parathyroid content of the calcium sensing receptor (CaSR), a gene directly stimulated by the calcitriol/VDR complex." (PMID 34950686, 2021).
atherosclerosis (13 papers, 2013 to 2025). A disease characterized by the build-up of fatty material and calcium deposition in the arterial wall resulting in partial or complete occlusion of the arterial lumen. "Curcuma oil has been shown to significantly regulate blood lipid indices such as total cholesterol (TC) and triglyceride (TG) and inflammatory factors such as interleukin-2 in atherosclerotic rats, which also provides a clinical basis for CASR in the treatment of CHD caused by atherosclerosis." (PMID 36016561, 2022). "Here the authors showed that CaSR expression was significantly increased in the atherosclerotic MI group compared to the MI controls, suggesting that CaSR plays an important role in MI caused by atherosclerosis." (PMID 31191301, 2019). "This study set out to investigate the in-vivo effects of adipocyte specific CaSR on inflammation and atherosclerosis development, by using newly established conditional adipocyte-specific CaSR deficient mice on an hyperlipidemic and atherosclerosis prone background." (PMID 34001955, 2021). "Therefore, we generated mature adipocyte specific CaSR deficient mice on an atherosclerosis prone background, to determine whether adipocyte CaSR indeed exacerbates atherosclerosis development by stimulating adipose tissue inflammation in-vivo." (PMID 34001955, 2021). "Moreover, altered CaSR function in diabetic patients may contribute to the development of atherosclerosis and increased cardiovascular risk." (PMID 25786244, 2015). "There have been reports of increased CaSR expression on monocytes from people suffering from type 2 diabetes, atherosclerosis, and rheumatoid arthritis." (PMID 35931812, 2022). "All of the in vitro and in vivo studies indicate that CaSR has a protective effect against atherosclerosis and vascular calcification by directly influencing and preventing mineral depositions in atherosclerotic plaques by SMCs." (PMID 33804544, 2021). "Several in-vitro studies demonstrated that CaSR plays a role in adipose tissue metabolism and inflammation, resulting in systemic inflammation and contributing to atherosclerosis development." (PMID 34001955, 2021). "Future studies should thereby focus on the exact role of progenitor, vascular or immune cell expressed CaSR to elucidate the effects of CaSR on adipose tissue inflammation and atherosclerosis development." (PMID 34001955, 2021). "Human circulating monocytes express the calcium-sensing receptor (CaSR) and are involved in atherosclerosis." (PMID 25134967, 2014). "The potential relationship between subclinical atherosclerosis assessed by vascular calcification and total and/or surface CaSR expression in human circulating monocytes should therefore be confirmed by future studies." (PMID 25134967, 2014). "In summary, CASR can resist atherosclerosis and alleviate the progression of CHD." (PMID 36016561, 2022). "The aim of this study was to investigate whether adipocyte CaSR plays a role in adipose tissue inflammation in-vivo and atherosclerosis development." (PMID 34001955, 2021). "The chemokine receptors, both classical and atypical, formyl-peptide receptors (FPRs), chemerin receptor 23 and the calcium-sensing receptor (CaSR) will be described in detail as they have been shown to play an important role in chronic inflammation and atherosclerosis." (PMID 31191301, 2019). "Besides its suspected role in atherosclerosis and MI, CaSR is also important in numerous other inflammatory diseases." (PMID 31191301, 2019). "Moreover, modulation of CaSR expression on VSMCs in CKD by calcimimetic agents (R-568) was demonstrated to effectively delay progression of vascular calcification and atherosclerosis in uremic apolipoprotein E-deficient mice." (PMID 25134967, 2014). "Therefore, CaSR may serve as a potential target for the treatment of atherosclerosis and vein grafting." (PMID 41208959, 2025).
atherosclerosis (continued). "In conclusion, adipocyte CaSR seems not to be involved in vAT inflammation in-vivo and does not influence atherosclerosis development in hyperlipidemic Apoe−/− mice." (PMID 34001955, 2021).
adenoma (12 papers, 2015 to 2025). A neoplasm arising from the epithelium. "More recently, global loss of CaSR has been reported in 5/10 carcinomas while all adenomas showed retained expression (p = 0.001), and only a single atypical adenoma (1/14) yielded global loss of expression." (PMID 35805976, 2022). "A decrease in the normal expression of CaSR in hyperplasia is detected statistically significantly less frequently than in adenoma (p≤0.01)." (PMID 37448244, 2023). "Colonic CaSR expression is detected in normal mucosa, early adenomas and polyps; it is already decreased in advanced adenomas, and is almost undetectable in late stage, poorly differentiated tumors." (PMID 25701758, 2015). "Other studies have further shown that CaSR and Myc deregulation may be linked to parathyroid gland tumorigenesis, especially significant downregulation of CaSR in SHPT compared to PHPT adenoma." (PMID 35681135, 2022). "Importantly, even histologically normal parathyroid tissue rimming adenomas already exhibited intermediate expression levels between true normal and adenoma tissues, suggesting that downregulation of CaSR expression may be an early event in tumorigenesis." (PMID 41210508, 2025). "Thus, 31% of carcinomas showed downregulation of CaSR, contrasting with adenomas and hyperplasia." (PMID 35805976, 2022). "In concordance with immunohistochemistry results, Epfn gene expression was increased in the parathyroid gland and inversely decreased in the adenoma, while the expressions of PTH and CCND1 were upregulated, and interestingly, the expression of CaSR was diminished in the adenoma." (PMID 40164571, 2025). "In this study, only a single adenoma featured a “carcinoma-like” irregular or absent CaSR staining pattern (1/104 in a mixed group of adenomas, primary multiglandular disease, secondary hyperplasia and tertiary hyperparathyroidism)." (PMID 35805976, 2022).
Bartter syndrome (12 papers, 2009 to 2025). "Whole-exome sequencing (WES) excluded pathogenic variants in renal tubulopathy genes including SLC12A3 (Gitelman syndrome), SLC12A1, CLCNKB, BSND, KCNJ1, MAGED2 (Bartter syndrome), and CASR, CLCNKA, KCNJ10 (hypokalemia-associated genes)." (PMID 40893942, 2025). "Four activating CaSR mutations cause additional renal wasting of sodium, chloride and other salts, a condition called Bartter syndrome (BS) type 5." (PMID 25506941, 2014). "Thus, Bartter syndrome, an autosomal disease, is caused by mutations of the bumetanide-sensitive Na–K–Cl (NKCC2) co-transporter, the renal outer-medullary potassium (ROMK) channel, the voltage-gated chloride channel, CLC-Kb, the CLC-Kb beta subunit, barttin, or the calcium-sensing receptor (CaSR)." (PMID 18446382, 2009). "Other causes of BS include mutations in the potassium voltage-gated channel subfamily J member 1 (KCNJ1) for Type II BS, chloride channel Kb (ClC-Kb) for Type III BS, Bartter syndrome, infantile, with sensorineural deafness (BSND) for Type IV BS, and calcium-sensing receptor (CaSR) for Type V BS." (PMID 31165006, 2019).
Familial hypocalciuric hypercalcemia type 1 (12 papers, 2010 to 2025). "The genetic testing for her family revealed that she, her brother, and her father were definitively diagnosed with FHH type 1 due to the heterozygous calcium-sensing receptor mutation (NM_00388:4:c.164C > T:p.Pro55Leu)." (PMID 35733207, 2022). "We experienced a 16-year-old female with FHH, in whom genetic testing identified the heterozygous calcium-sensing receptor mutation (NM_00388:4:c.164C > T:p.Pro55Leu) as pathogenic, permitting a definitive diagnosis of FHH type 1." (PMID 35733207, 2022). "These families often, but not always, present with germline mutations in either MEN1, CDC73, or the calcium sensing receptor (CaSR) gene, of which the latter is also associated to the development of familial hypocalciuric hypercalcemia type 1 (FHH1)." (PMID 33269427, 2021). "Genetic testing revealed a novel heterozygous CASR p.Tyr161* mutation and a homozygous SLC12A3 p.Thr60Met mutation, which ultimately confirmed the diagnosis of familial hypocalciuric hypercalcemia type 1 (FHH1) combined with GS." (PMID 40070587, 2025). "Loss of function mutations in the CASR, GNA11, or AP2S1 genes cause FHH type 1 (FHH1), FHH type 2 (FHH2), and FHH type 3 (FHH3), respectively." (PMID 35733207, 2022). "The importance of CaSR-mediated signaling for Ca2+ homeostasis is confirmed by germline loss-of-function mutations in CASR (MIM: 145980; 239200), GNA11 (MIM: 145981), and AP2S1 (MIM: 600740) that cause familial hypocalciuric hypercalcemia types 1–3 (FHH1-3), respectively." (PMID 32386559, 2020).
Sepsis (12 papers, 2015 to 2026). Sepsis is defined as life-threatening organ dysfunction caused by a dysregulated host response to infection. "The dual role of the calcium-sensing receptor (CaSR) in sepsis has also drawn attention: Its activation can both alleviate organ dysfunction and potentially exacerbate inflammatory responses." (PMID 41041277, 2025). "Recently, the CaSR was considered to be a novel target for the treatment of sepsis-induced CRS (type 5 CRS), as the CaSR mediates sepsis-induced oxidative stress, inflammation, apoptosis, and cardiorenal dysfunction." (PMID 36231037, 2022). "In our previous study, we demonstrated that CaSR protein in T lymphocytes regulated the production of cytokines and apoptosis through the NF-κB signaling pathway in sepsis." (PMID 29081886, 2017). "Our team has proved that CaSR in peripheral T lymphocytes contributed to cytokine secretion and apoptosis involved in the NF-κB signaling pathway in sepsis." (PMID 27563892, 2016). "In addition, the sepsis-increased CaSR expression in T lymphocytes (circulating or resident in heart or kidney tissues) promoted the release of TNF-α and IL-4 cytokines and induced tissue apoptosis and injury." (PMID 36231037, 2022). "In the CLP-induced sepsis, calcium-sensing receptor activation promotes T cell apoptosis and the secretion of the proinflammatory cytokine TNF-α and the anti-inflammatory cytokine IL-4 probably through NF-κB and partial ERK and JNK signal transduction pathways." (PMID 32908632, 2020). "CaSR can induce cardiomyocyte apoptosis in AMI and enhance T cells to secrete some kinds of cytokines in sepsis." (PMID 29081886, 2017).
Bartter syndrome type 5 (11 papers, 2009 to 2026). "In contrast, gain-of-function CASR variants, historically labeled "type V Bartter syndrome", are now more appropriately described as CaSR-associated Bartter-like phenotypes within the broader spectrum of disorders of calcium homeostasis." (PMID 42042082, 2026). "The importance of the CaSR in this process has been proven by identification of activating mutations in the CaSR gene, which cause Bartter syndrome type 5, a human disease characterized by excessive wasting of NaCl and other electrolytes." (PMID 23340319, 2013). "This suggests that the additional features that occur in Bartter syndrome type V when compared to ADHH are due to severe gain-of-function mutations of the CaSR." (PMID 18446382, 2009). "The differential diagnoses in our case were primary hypoparathyroidism, Bartter syndrome type 5 (CaSR mutation), Gitelman syndrome, and claudin mutations involving the paracellular pathway of magnesium and calcium at the thick ascending limb of the loop of Henle." (PMID 40454415, 2025). "Four activating mutations of the CaSR cause additional renal sodium, chloride and magnesium wasting which results in hyperreninemia, hyperaldosteronism, hypokalemia, and metabolic alkalosis, a condition called Bartter syndrome type 5 (BS type 5)." (PMID 25506941, 2014). "Activating mutations of calcium-sensing receptor (CaSR) suppresses the NKCC2 and ROMK expression to induce type 5 Bartter syndrome." (PMID 32758178, 2020). "However, gain-of-function CaSR mutations result in autosomal dominant hypocalcemia with hypercalciuria (ADHH) and Bartter’s syndrome type V." (PMID 18446382, 2009).